ALB (albumin)
Diseases named in the same sentence as ALB in open-access papers (continued):
Sharing a sentence is not in itself a finding about the gene and the disease.
marasmus (4 papers, 2014 to 2022). The lack of sufficient energy or protein to meet the body's metabolic demands, as a result of either an inadequate dietary intake of protein, intake of poor quality dietary protein, increased demands due to disease, or increased nutrient losses. "This sub-cohort comprised children with kwashiorkor and marasmus matched on exact serum albumin levels and served as the discovery cohort for this study." (PMID 35398787, 2022). "This suggests a longstanding nutritional impairment in these patients, especially since albumin levels may be normal in the context of prolonged malnutrition (including in the case of marasmus) due to adaptive changes." (PMID 34829464, 2021). "Serum levels of BChE, total protein, and albumin are lower in malnourished children with marasmus than those measured in normal children; these values tend to increase after 3 weeks of nutritional rehabilitation, and a similar trend in serum levels of BChE has been observed in undernourished adults." (PMID 29736152, 2018). "We recognize that matching patients by admission serum albumin for the specific objective of examining albumin-independent mechanisms precludes comparison with the full spectrum of marasmus cases, however that was not our intention." (PMID 35398787, 2022).
mesothelioma (4 papers, 2013 to 2025). A usually malignant and aggressive neoplasm of the mesothelium which is often associated with exposure to asbestos. "In mesothelioma patients, high CRP and low albumin levels have been strongly associated with poor prognosis." (PMID 40282547, 2025). "Xenograft tumors established with human mesothelioma cells were treated with an EphB4 inhibitor (monomeric soluble EphB4 fused to human serum albumin, or sEphB4-HSA)." (PMID 23721559, 2013). "The loss of resistance indicates that the non-cancer primary cells were more sensitive than mesothelioma cells to the treatment protocol, ie. to the sudden removal of growth factors and/or albumin." (PMID 30157247, 2018).
metastatic prostate carcinoma (4 papers, 2020 to 2024). A carcinoma that arises from the prostate gland and has spread to other anatomic sites. "Elevated pretreatment ALB was a favorable prognostic factor for PFS, cancer‐specific survival, and OS of the metastatic prostate cancer patients." (PMID 34254464, 2021).
muscular dystrophy (4 papers, 2017 to 2025). Muscular dystrophy (MD) refers to a group of more than 30 genetic diseases characterized by progressive weakness and degeneration of the skeletal muscles that control movement. "It has been reported that EBD binds to serum albumin and flows into myofibers with increased membrane permeability, such as myofibers in mdx mice (a mouse model of muscular dystrophy) and those with damaged cell membranes due to mechanical stimulation." (PMID 38355142, 2024). "During muscular dystrophy, the absence of dystrophin protein severely diminishes sarcolemmal stability and hence, proteins like albumin, which are otherwise restricted to circulation, are able to cross the sarcolemma and accumulate in myofibers." (PMID 29228710, 2017).
nephrocalcinosis (4 papers, 2018 to 2025). Nephrocalcinosis is a disorder that occurs when too much calcium is deposited in the kidneys. "The CKD cats with nephrocalcinosis had higher plasma concentrations of tCa, calcium phosphate product (CaPP), albumin and total magnesium concentrations and alanine aminotransferase (ALT) activity compared with CKD cats without nephrocalcinosis." (PMID 38438128, 2024).
normocytic anemia (4 papers, 2018 to 2024). Anemia in which the red blood cell volume is normal. "Laboratory investigations revealed normocytic anemia (hemoglobin, 100 g/L), hypoproteinemia (albumin, 33.7 g/L), elevated inflammatory marker levels (CRP, 13.77 mg/L; ESR, 50 mm/h), and a high platelet count of 320 × 109/L." (PMID 37798676, 2023). "Laboratory investigations revealed normocytic anemia (hemoglobin, 97 g/L), hypoproteinemia (albumin, 29.6 g/L), and elevated inflammatory marker levels [C-reactive protein (CRP), 10.47 mg/L; erythrocyte sedimentation rate (ESR), 28 mm/h]." (PMID 37798676, 2023).
obstructive jaundice (4 papers, 2018 to 2023). A finding indicating increased bilirubin levels in the blood and urine, due to intrahepatic or extrahepatic obstruction of the biliary system. "Univariate logistic regression analysis revealed obstructive jaundice (P < 0.001), preoperative blood glucose (P < 0.001), preoperative albumin (P = 0.034), preoperative total bilirubin (P < 0.001), preoperative CA19-9 (P < 0.001), preoperative CA125 (P = 0.040), preoperative fibrinogen (P < 0.001)." (PMID 37723476, 2023). "According to whether patients had preoperative obstructive jaundice and abnormalities of GGT or ALB, we further investigated the predictive effect of GAR in each different subgroups." (PMID 30632317, 2019).
obstructive lung disease (4 papers, 2016 to 2024). "The BARC index is comprised of variables commonly included in established predictive indexes, such as airway obstruction, age, smoking status and dyspnoea assessment, as well as several comorbidities and blood biomarkers linked to general health (including serum albumin and haemoglobin)." (PMID 30947728, 2019).
oral cavity cancer (4 papers, 2018 to 2022). A primary or metastatic malignant neoplasm involving the oral cavity. "PET/CT lymphoscintigraphy was performed after peritumoural injection of 89Zr-nanocolloidal albumin in five patients with oral cavity carcinoma planned for surgical resection." (PMID 29445878, 2018).
oral mucositis (4 papers, 2022 to 2024). Inflammation of the mucous membranes of any of the structures in the mouth. "Radiation-induced oral mucositis (ROM) was strongly associated with nutritional status, body weight, and serum albumin levels." (PMID 37350940, 2023). "Oral mucositis and dysphagia occurred frequently, which may prevent the patient from oral feeding and result in malnourishment and low serum albumin levels." (PMID 36531036, 2022). "This suggests that aggressive treatment aimed at controlling lymphocyte counts and albumin levels may ameliorate the PNI level more favourably and reduce the severity of oral mucositis." (PMID 39665402, 2024).
ovarian hyperstimulation syndrome (4 papers, 2011 to 2019). A complication of ovulation induction in infertility treatment. "The authors concluded in the abstract that albumin showed a clear benefit at preventing severe ovarian hyperstimulation syndrome, although they were much more cautious in the main text." (PMID 21349195, 2011).
placenta previa (4 papers, 2021 to 2025). "Gestational age, primipara, placenta previa, antenatal corticosteroid therapy, delivery mode, and neonatal serum albumin level were associated with RDS in the late-preterm infant." (PMID 34485188, 2021). "After adjustment for gestational age, logistic regression analysis showed that neonatal serum albumin level, placenta previa, and delivery mode were independent risk factors for RDS in late-preterm infants." (PMID 34485188, 2021). "After adjustment for gestational age, the results suggested that neonatal serum albumin levels, placenta previa, and delivery mode were independent influencing factors of RDS in late-term preterm infants." (PMID 34485188, 2021). "Seven independent prognostic variables, including antepartum albumin, assisted reproductive technology, hypertensive disorders of pregnancy, placenta previa, placenta accrete spectrum, intrapartum cesarean delivered, and estimated weights of twins, were used to build the nomogram." (PMID 37144027, 2023).
psychological distress (4 papers, 2018 to 2025). "While the mechanisms underlying cancer-related fatigue are still unclear, previous reports point to associations with psychological distress, increased inflammation, and, in some cases, decreased hemoglobin and albumin levels." (PMID 30131851, 2018). "In addition, lower levels of albumin were independently associated with high levels of psychological distress." (PMID 32658906, 2020). "The levels of psychological distress in female medical students may be associated with nutritional markers such as albumin, and with menstrual-related symptoms." (PMID 32658906, 2020). "In PLS-SEM analysis, a latent global psychological distress measure was directly related to β2-microglobulin and inversely related to albumin and calcium (R2 = 0.47)." (PMID 41463102, 2025). "During cCHRT, a significant increase in albumin and psychological distress was observed, as well as a significant decrease in platelet, N-acetyl-cysteine, tyrosine, and phenylalanine, in patients who received iCHT." (PMID 38203359, 2023). "The crude analysis revealed that lower levels of Hb and albumin, presence of PMS, and higher MDS-scores were associated with high levels of psychological distress." (PMID 32658906, 2020). "Serum albumin levels were associated with psychological distress, while lipid metabolite levels were not." (PMID 32658906, 2020).
Pulmonary hemorrhage (4 papers, 2014 to 2025). Pulmonary hemorrhage is a bleeding within the lungs. "Pulmonary hemorrhage leads to the leakage of blood components into alveolar spaces, causing surfactant inactivation through interactions with plasma proteins such as albumin and fibrinogen and cell-free hemoglobin." (PMID 41367478, 2025). "We also found that 2 and 5 mg/kg doses caused pulmonary hemorrhage and edema as indicated by increased BAL haemoglobin and albumin levels." (PMID 25331813, 2014). "Histological analysis of pulmonary hemorrhage indicated a positive effect of senicapoc on alveolar–capillary barrier function, but this was not supported by measurements of albumin content and total protein in the bronchoalveolar lavage fluid." (PMID 33870468, 2021).
purpura (4 papers, 2016 to 2025). A small blood vessel hemorrhage into the skin and/or mucous membranes. "Rare onset age, purpura above the waist, vomiting, high neutrophil-to-lymphocyte ratio, and decreased serum albumin are associated with severe GI involvement." (PMID 37614903, 2023). "Rare onset age (<3 years or within 13–17 years), purpura above the waist, vomiting, high neutrophil-to-lymphocyte ratio, and decreased serum albumin were factors associated with severe GI involvement." (PMID 37614903, 2023). "Several factors have been associated with severe GIS involvement, including early or late onset age (< 3 years or 13–17 years), purpura on the trunk, vomiting, a high neutrophil-to-lymphocyte ratio, and decreased serum albumin levels." (PMID 40310537, 2025). "For animals in group 5 (albumin, positive control), strong signs of labored respiration, unsteady gait and/or purpura, as well as weak signs of restlessness, piloerection, and nose scratching, were observed in six animals within 5 min of intravenous challenge." (PMID 27768591, 2016). "According to the input feature indexes, the top ten important feature indicators output by the XGBoost model are as follows: NAG, RBP, IgA, age, recurrence of purpura, purpura area, abdominal pain, 24-h urinary protein quantification, percentage of neutrophils, and serum albumin." (PMID 35651924, 2022).
relapsing-remitting MS (4 papers, 2019 to 2023). "In a monocentric longitudinal retrospecitve cohort study, KFLC-index ([CSF KFLC/serum KFLC]/[CSF albumin/serum albumin]) measured by latex-enhanced immunonephelometry was prospectively determined as part of the diagnostic workup in patients with early relapsing-remitting MS (RRMS, n=77)." (PMID 36742305, 2023).
respiratory distress syndrome (4 papers, 2008 to 2024). "Beginning in the 1950s, albumin has been utilized to reduce morbidity and mortality in preterm neonates, initially in respiratory distress syndrome." (PMID 37888650, 2023). "In pre-term infants with respiratory distress syndrome, intravenous administration of 1 g/kg 25% albumin over a 10 min period increased blood volume (p < 0.0005) and mean arterial blood pressure (p < 0.05) within 10 min after infusion was completed." (PMID 18318896, 2008).
Respiratory insufficiency (4 papers, 2020 to 2022). "Decreased albumin may result in lower pulmonary oncotic pressure contributing to increased fluid extravasation, which, together with the higher vascular permeability underlying the respiratory insufficiency, would further worsen lung edema." (PMID 36558522, 2022).
retinal degeneration (4 papers, 2019 to 2025). Degeneration of the retina. "Breakdown of the retinal epithelial barrier was then evaluated by albumin diffusion into the retina 8 days following light-induced retinal degeneration." (PMID 32882879, 2020).
retinal oedema (4 papers, 2018 to 2025). "The resulting blood–retinal barrier (BRB) breakdown leads to increased vascular permeability, which was detected immunohistochemically by the extravasation of plasma albumin as a vascular tracer, and ensuing severe, diffuse, vasogenic retinal oedema." (PMID 38275918, 2023). "Although we detected albumin leakage, indicative of blood–retinal barrier breakdown, the microscopic levels of leakage may not cause significant retinal oedema." (PMID 30019207, 2018).
sarcoidosis (4 papers, 2012 to 2026). Sarcoidosis is a multisystemic disorder of unknown cause characterized by the formation of immune granulomas in involved organs. "Sarcoidosis patients with sHTN had a significantly lower mean albumin level compared with normotensives (3.44 versus 3.77 gm/dL, resp., P = 0.004)." (PMID 27433355, 2016). "In sarcoidosis, increased levels of BALF albumin are thought to result from an influx of plasma albumin into the alveoli." (PMID 22650152, 2012). "Furthermore, sarcoidosis patients have previously been reported with elevated BAL levels of albumin, suggested to be related to the chronic inflammation and not the lavage procedure itself." (PMID 27259755, 2016).
septic peritonitis (4 papers, 2014 to 2025). Septic peritonitis is an inflammatory condition of the peritoneum that occurs secondary to microbial contamination. "It seems well-tolerated, can increase serum albumin concentrations in dogs with septic peritonitis, and can increase albumin and COP in healthy dogs." (PMID 33869319, 2021). "A prospective, randomized trial of 5% canine albumin compared to clinician-directed therapy in 14 dogs with septic peritonitis found that albumin levels remained increased 24 h after transfusion in the albumin group, but the study was not powered to evaluate mortality as an outcome." (PMID 33718468, 2021).
sinusitis (4 papers, 2020 to 2024). An acute or chronic inflammatory process affecting the mucous membranes of any sinus cavity. "A new protocol with albumin-concentrated growth factor (CGF) is investigated through Piezosurgery as a minimally invasive alternative to sinus-floor-augmentation that is associated with high morbidity and high incidence of sinusitis." (PMID 37729926, 2024).
sudden sensorineural hearing loss (4 papers, 2020 to 2023). Sensorineural hearing loss which develops suddenly over a period of hours or a few days. "Although C-reactive protein/albumin ratio was found to be lower in sudden hearing loss patients who responded to treatment compared to those who did not, the difference between two groups was not statistically significant." (PMID 30522831, 2020). "Increased levels of fibrinogen-albumin ratio may be predictive for poor prognosis in patients with sudden sensorineural hearing loss." (PMID 32788059, 2021). "In univariate analysis, age, type of hearing curve at the initial diagnosis, acute phase, total protein level, albumin level, sudden deafness site, and hyperbaric oxygen treatment were identified as the risk factors for poor prognosis in patients with sudden deafness." (PMID 35720064, 2022). "Through univariate analysis, age, type of hearing curve at the initial diagnosis, acute phase, total protein level, albumin level, sudden deafness site, and hyperbaric oxygen treatment were found to be the significant risk factors for poor prognosis of patients with sudden onset deafness." (PMID 35720064, 2022).
systemic vasculitis (4 papers, 2022 to 2026). "Low albumin levels may indicate chronic inflammation or nutritional effects secondary to systemic vasculitis, while anti‐DNA antibodies typically associated with SLE could suggest overlapping immunological pathways or coexisting autoimmune features." (PMID 41583997, 2026). "There were statistically significant differences between the LTBI group and non-LTBI group in terms of systemic vasculitis type (P = 0.010), albumin levels (P = 0.034), erythrocyte sedimentation rate (P = 0.016), and corticosteroid dosage (P = 0.047)." (PMID 39838164, 2025).
teratoma (4 papers, 2015 to 2023). A non-seminomatous germ cell tumor characterized by the presence of various tissues which correspond to the different germinal layers (endoderm, mesoderm, and ectoderm). "For example, albumin, the most abundant protein in whole blood, was not significantly enriched in teratoma-derived biotinylated serum proteome (average log2TMT ratio = −0.51 ± 0.17 for serum and −0.27 ± 0.13 for teratoma)." (PMID 33888706, 2021). "Other baseline, tumor and pre-operative characteristics, including primary tumor laterality, pathological stage, whether teratoma existed, the IGCCC level, red blood cell count, hemoglobin level, white blood cell count, platelet count, albumin level, and total bilirubin level were also comparable." (PMID 37332060, 2023). "Human ALB and AFP were detected between the concentrations of approximately 0.6–1.6 and 1.7–2.9 μg/mL, respectively, in the sera of mice bearing teratomas but not in those of normal mice." (PMID 25875613, 2015).
thymoma (4 papers, 2016 to 2024). A neoplasm arising from the epithelial cells of the thymus. "Due to the constitutive expression of peptides from the chicken egg albumin (Ovalbumin, OVA) bound to MHC class I molecules and to the surface expression of PDL1 and PDL2 molecules, EG.7-OVA thymoma is considered an immunogenic tumor model." (PMID 32290265, 2020).
vulvar cancer (4 papers, 2019 to 2024). "The aim of this study was to investigate the association between pre-treatment serum albumin and postoperative complications and prognosis in patients with vulvar cancer undergoing surgery." (PMID 31468203, 2019). "In this study, patients with low albumin levels had lower overall survival (OS) compared to women with normal albumin levels and vulvar cancer, after undergoing surgery." (PMID 39459466, 2024). "An invaluable study published in 2019 examined the correlation between albumin levels, postoperative complications, and overall survival in relation to vulvar cancer." (PMID 39459466, 2024). "The aim of this study was to investigate the prognostic and predictive value of pre-treatment serum albumin levels for survival and postoperative complications in patients with vulvar cancer undergoing surgery." (PMID 31468203, 2019). "Also, studies have shown that low serum ALB is an unfavorable determinant in other malignancies, including oral, breast, and vulvar cancers 30-32." (PMID 34539891, 2021). "In accordance with previously published literature in other solid tumors, our results suggest a strong association between low pre-treatment serum albumin levels and shorter OS in patients with vulvar cancer independent of other established prognostic parameters." (PMID 31468203, 2019). "The present study aims to evaluate the pretherapeutic Fibrinogen-Albumin-Ratio Index (FARI), as currently reliable biomarkers to predict therapy response and prognosis of patients with advanced vulvar cancer are missing." (PMID 36579608, 2022).